ZNF362 (zinc finger protein 362)
Description:
May be involved in transcriptional regulation.
Synonyms: FLJ25476; lin-29; RN; LIN29
Tractability: PROTAC: UniProt records ubiquitination sites on it.
Gene: Protein-coding gene on chromosome 1 (33,256,359 to 33,300,719, forward strand). Ensembl gene ENSG00000160094.
Subcellular location: Nucleus
Subcellular location (Human Protein Atlas): Nucleoplasm; Nucleoli
Gene Ontology:
Molecular function: DNA-binding transcription factor activity; RNA polymerase II cis-regulatory region sequence-specific DNA binding
Biological process: regulation of transcription by RNA polymerase II
Cellular component: nucleus
Genetic constraint (gnomAD): Loss-of-function variants: 11 observed, 40.93 expected, observed/expected ratio (o/e) 0.27, 90% interval 0.17 to 0.44. The upper end of that interval is the gene's LOEUF score, 0.44, which puts it in group 1 of 6, group 1 being the genes least tolerant of losing a copy. Missense variants: 360 observed, 555.47 expected, observed/expected ratio (o/e) 0.65, 90% interval 0.59 to 0.71. Synonymous variants: 255 observed, 246.81 expected, observed/expected ratio (o/e) 1.03, 90% interval 0.93 to 1.15.
Homologues: Orthologues: macaque ZNF362 (99% identical), guinea pig ZNF362 (99% identical), dog ZNF362 (98% identical), pig ZNF362 (98% identical), mouse Zfp362 (98% identical), rat Zfp362 (98% identical), chimpanzee ZNF362 (98% identical), rabbit ZNF362 (97% identical), tropical clawed frog znf362 (88% identical), zebrafish znf362b (76% identical), zebrafish znf362a (75% identical). Paralogues in human: ZNF384 (47% identical), ZNF143 (22% identical), PRDM1 (21% identical), PRDM14 (21% identical), ZNF76 (20% identical), PATZ1 (20% identical), ZNF281 (19% identical), PRDM10 (19% identical), MTF1 (18% identical), ZBTB16 (18% identical), ZNF451 (18% identical), ZNF575 (17% identical), and 24 more.
Diseases named in the same sentence as ZNF362 in open-access papers:
ZNF362 is named in the same sentence as 4 diseases in open-access papers, as found by Europe PMC text mining. Sharing a sentence is not in itself a finding about the gene and the disease. The quoted sentences say what the papers report.
Anxiety (1 paper, 2025). Intense feelings of nervousness, tension, or panic often arise in response to interpersonal stresses. "Previous research has identified an association between the gene ZNF362 and the positive and negative dimensions of the Marder factor scores, which are linked to specific psychopathological features such as uncontrolled hostility/excitement and anxiety/depression." (PMID 39999171, 2025).
ischemic stroke (1 paper, 2025). A stroke disorder caused by obstruction of blood flow to the brain, due to thrombotic (local blood clot formation) or embolic (due to a blood clot or other material traveling from another site) event. "In ischemic stroke, we found that MPO, CALCRL, PPP5C, KTN1-AS1, CCR1, CTB-50L17.9, CCR9, ZNF362, ZIK1, ELP5, CKAP2, NUP88, and SEC16A show risk effects (OR > 1)." (PMID 40624693, 2025).
ZNF362 also shares sentences with these, for which no sentence is quoted: asthma (1 paper); depression (1).